OR8S1 (olfactory receptor family 8 subfamily S member 1)
Description:
Odorant receptor.
Gene: Protein-coding gene on chromosome 12 (48,525,632 to 48,526,570, forward strand). Ensembl gene ENSG00000284723.
Subcellular location: Cell membrane
Pathways (Reactome):
Sensory Perception: Expression and translocation of olfactory receptors
Genetic constraint (gnomAD): Missense variants: 357 observed, 380.43 expected, observed/expected ratio (o/e) 0.94, 90% interval 0.86 to 1.02. Synonymous variants: 145 observed, 156.99 expected, observed/expected ratio (o/e) 0.92, 90% interval 0.81 to 1.06.
Homologues: Orthologues: chimpanzee OR8S1 (93% identical), macaque OR8S1 (87% identical), pig OR8S1 (85% identical), dog OR8S1 (84% identical), mouse Or8s16 (59% identical), rat Or8s16 (59% identical). Paralogues in human: OR5BS1 (49% identical), OR7A5 (45% identical), OR7C1 (44% identical), OR1J1 (44% identical), OR7D4 (44% identical), OR1F1 (44% identical), OR7G3 (44% identical), OR7A10 (43% identical), OR7D2 (43% identical), OR1L6 (43% identical), OR1J2 (43% identical), OR1J4 (43% identical), and 116 more.
Diseases named in the same sentence as OR8S1 in open-access papers:
OR8S1 is named in the same sentence as 4 diseases in open-access papers, as found by Europe PMC text mining. Sharing a sentence is not in itself a finding about the gene and the disease.
OR8S1 shares sentences with these, for which no sentence is quoted: cancer (1 paper); infection (1); neurodegenerative disease (1); Parkinson disease (1).